BECN1 (beclin 1)
Diseases named in the same sentence as BECN1 in open-access papers (continued):
Sharing a sentence is not in itself a finding about the gene and the disease.
cancer (continued). "These Beclin 1 mimetics represent promising leads to develop novel molecular therapy for human cancer with Bcl-2/xL overexpression and resistant to conventional chemo/radiotherapy." (PMID 28881653, 2017). "These Beclin 1 mimetics will be invaluable tools for developing novel autophagy inducers, better understanding the roles of autophagy in cancer, and will contribute to cancer therapy." (PMID 28881653, 2017). "Beclin-1 protein levels were increased in cachectic cancer patients, suggesting autophagy induction." (PMID 27459917, 2016). "It is well established that the suppression of Beclin-1 expression results in tumorigenesis via impaired autophagy in cancer." (PMID 27174920, 2016). "In 24 out of 96 (25.0%) adjacent NNM tissues, and 57/96 (59.4%) cancer tissues, high expression of Beclin-1 was detected." (PMID 28070138, 2016). "Beclin-1 mRNA levels were unchanged, while Beclin-1 protein expression was significantly increased in the skeletal muscle of cachectic cancer patients suggesting autophagy activation." (PMID 27459917, 2016). "Inhibition of autophagy by silencing of Beclin 1 expression reduced the cancer cell survival and invasion." (PMID 26910278, 2016). "Downregulation of beclin-1 reduces cell autophagy and prolongs the life cancer cells, leading to increased development of cancers." (PMID 27153056, 2016). "Immunoreactivity of the autophagy-associated markers, beclin 1 and LC3, in carcinoma cells increased in 14 % and 52 % of the patients, respectively, following the exemestane treatment." (PMID 26984766, 2016). "Another implication of our finding relates to the potential relationship of MK3 deletion and Beclin 1 S90 phosphorylation in cancer development." (PMID 25693418, 2015). "Decreased expression of Beclin-1 leads to defects of autophagy in early tumorigenesis in certain cancers, while increased expression of Beclin-1 is a characteristic of an increase in autophagy survival in established tumors." (PMID 26494988, 2015). "Several studies have shown a decrease of Beclin-1 protein immunoexpression in a number of cancers, but several other studies have detected an increase of Beclin-1 protein expression in cancer compared to normal tissues." (PMID 26494988, 2015). "Rapamycin, which failed as a cancer monotherapy, acts proximal to the Becn1/Ulk1/Vps34 autophagy initiation complex by inhibiting mTORC1." (PMID 26418751, 2015). "Further study is needed to not only elucidate the complex and context-dependent roles of Beclin-1 in ovarian and other tumors, but also to understand the often paradoxical nature of autophagy in cancer biology." (PMID 26239434, 2015). "Mice harboring heterozygous disruption of the Becn1 gene (Becn1+/−) are viable but develop malignancies at higher rates than wild-type littermates." (PMID 26239434, 2015). "Next, we examined the molecular pathway responsible for the aggressive phenotype of beclin-1-negative cancer cells that have concomitant stromal beclin-1 expression." (PMID 25955408, 2015). "In general, studies examining differential Beclin-1 expression have compared cancer tissue with normal control tissue, as opposed to comparing two different groups within the same pool of cancers." (PMID 25487826, 2015). "Immunohistochemistry demonstrated that cancer cells and stromal mesenchymal cells expressed beclin-1 in 68 and 38 of 115 invasive ductal cancers, respectively." (PMID 25955408, 2015). "Bcl-2 was reported to act as an anti-autophagy protein via its inhibitory interaction with Beclin-1 in various cancer cells." (PMID 26311737, 2015). "We previously reported that autophagy occurs after cetuximab treatment and that knockdown of autophagy regulatory genes, such as Beclin 1 or Atg7, or treatment with the lysosome inhibitor chloroquine sensitized cancer cells to cetuximab-induced apoptosis." (PMID 25871473, 2015). "The evolutionarily conserved autophagy gene beclin 1 (vps30/atg6) is frequently inactivated at one locus in several cancers." (PMID 24967584, 2014).
cancer (continued). "Conversely, only 8 out of 32 (25%) patients in CR were bearing a cancer with a ≤20% of BECLIN 1-positive cells." (PMID 25136588, 2014). "The interaction between Bcl-XL and Beclin 1 can inhibit autophagy and thus promote the progression of malignant tumors." (PMID 24675697, 2014). "Fourteen (of the 61) cancers examined showed positive for BECLIN 1 in a percentage of cells ranging from 20% to 90%." (PMID 25136588, 2014). "Specific Beclin-1 staining was predominantly observed at the cytoplasm membrane in normal cervical epithelial and cancer tissues." (PMID 25202355, 2014). "For example, the knockdown of ATG5 or BECN1 in cancer cells containing defects in apoptosis leads to a marked reduction in autophagic cell death (as well as autophagic response) in response to cell death stimuli with no signs of apoptosis." (PMID 25317422, 2014). "The expression of Beclin-1 was significantly decreased in cancer tissues when compared with that in normal cervical tissues." (PMID 25202355, 2014). "Results from the present study provide further clues explaining Beclin 1 regulation in autophagy induced by cancer treatments." (PMID 24438216, 2014). "Many recent studies have investigated the levels of Beclin 1 expression in malignant tumors and the relationship between these level and the prognoses of these tumors." (PMID 24675697, 2014). "The expression of autophagy-related proteins (particularly LC3 and BECN1) has been reported to be a prognostic factor in various human cancers, but the results are conflicting." (PMID 24723943, 2014). "At present, elevation of Beclin 1 protein levels in human cancers and decreases in Beclin 1 expression have been reported." (PMID 24527069, 2014). "Beyond the requirement of autophagy for survival of Ras-driven cancer cells, Ras activation also promotes cell signaling events involved in the induction of autophagy by the upregulation of Noxa and Beclin-1 expression." (PMID 25328887, 2014). "Beclin-1 as part of the Beclin-1-Vps34-Vps15 core complex has been reported to induce considerable autophagic cell death, inhibit cancer cell growth, and act as an important molecular switch between autophagy and apoptosis." (PMID 24878898, 2014). "Aberrant expression of Beclin-1, an important autophagic gene, has been reported in various human cancers." (PMID 24885292, 2014). "Beclin 1 participates in development, autophagy, differentiation, anti- apoptosis, neurodegeneration, tumorigenesis and cancer progression." (PMID 25196438, 2014). "From previous studies it appears that Beclin-1-independent autophagy can occur in cancer cells as well as neurons following treatment with agents that induce cell death." (PMID 24681637, 2014). "Several mechanisms that describe how autophagy induced by beclin-1 prevents cancer can be considered." (PMID 23935917, 2013). "Beclin-1, the product of autophagy promoting gene Beclin-1 (Atg6), has been shown to regulate autophagy in cancer cells." (PMID 23853725, 2013). "Overexpression of Beclin-1 in human cervical cancer cells has been reported to induce massive autophagic cell death and inhibit cancer cell growth." (PMID 24053190, 2013). "Beclin 1, as a key regulator of autophagy, gets much attention in recent years due to its involvement in carcinogenesis and cancer progression." (PMID 24260370, 2013). "The relationship between the expression pattern of Beclin-1 and the prognosis was controversial in studies of human cancer." (PMID 23578251, 2013). "Cytoplasmic Beclin-1 expression was significantly weaker in cancer cells than in nearby normal mammary glands (p < 0.001)." (PMID 23578251, 2013). "Considering the prognostic impact of Beclin 1 protein in different human cancers, reports have drawn complicated conclusions." (PMID 24260370, 2013).
cancer (continued). "Two mechanisms by which BECN1 haploinsufficiency promotes cancer are impaired autophagy and increased cell proliferation." (PMID 23833647, 2013). "Beclin-1 was found to be deleted in large portions (50–75%) of various types of human cancers, including breast and ovarian." (PMID 23563240, 2013). "The normal mammary glands near the cancer cells showed weak or moderate cytoplasmic reactivity and variable nuclear expression of Beclin-1." (PMID 23578251, 2013). "A reduced Beclin 1 expression has been indeed demonstrated in several human cancers, including glioblastomas, ovarian, lung, and esophageal cancers." (PMID 22928777, 2012). "Specific Beclin 1 staining was mostly found on the membrane-plasma and cytoplasm in the cancer cells, occasionally the nucleus." (PMID 23029344, 2012). "Beclin 1, a key regulator of autophagy formation, was found overexpression in a variety of human cancers." (PMID 23029344, 2012). "The expression of Beclin 1, the mammalian homolog of yeast autophagy gene Atg6 which is critical for induction of autophagy, is decreased in many cancer tissues and cancer cell lines." (PMID 22745748, 2012). "Beclin 1 is the mammalian orthologue of the yeast Vps30/Apg6 gene, required for autophagosome formation, and is monoallelically deleted in a high percentage of human carcinomas." (PMID 22540380, 2012). "Various cancer cells exhibit decreased Beclin 1 levels and the anti-cancer agent tamoxifen increases expression of this protein." (PMID 21217818, 2010). "Normal colon area showed invariably a weak Beclin 1 staining of epithelial cells, and this intensity was considered as normal-like for the subsequent scoring of cancer areas." (PMID 20842118, 2010). "The existing data on the prognostic role of Beclin 1 in human carcinomas are rather scarce and contradictory." (PMID 20842118, 2010). "Beclin 1, a protein required for autophagy, is frequently lost in ovarian, breast, andprostate cancers, and beclin 1 +/− mutant mice are prone to increase incidenceof tumors derived from epithelial or lymphopoietic tissues." (PMID 18509489, 2008). "Moreover, comparison of their expression in several cancer types (from the TCGA database) showed that BECN1 (the key autophagy factor) was specifically overexpressed in DLBCL samples." (PMID 41415285, 2025). "Therefore, the roles of Beclin-1 and p62 in cynaropicrin-induced autophagy need to be redefined depending on the cancer cell line used." (PMID 40295200, 2025). "Induces autophagy-associated apoptosis in cancer cells.Inhibits the PI3K/AKT/mTOR pathway by reducing p-PI3K expression.Increases ROS production, leading to AMPK activation, upregulation of ULK1, and phosphorylation of Beclin-1, thereby promoting autophagy." (PMID 41211420, 2025). "Furthermore, BNIP3L and BECN1 expression potentially inhibited the cell cycle and DNA damage pathways (16–19%) in pan-cancer." (PMID 39859167, 2025). "Here, we identified an autophagic vulnerability in cancers with BAP1 mutations involving the oncogenic tyrosine kinase SRC and the autophagy protein BECN1 that can be therapeutically targeted, opening the possibility of novel treatments specific for tumors with BAP1 loss." (PMID 40754831, 2025). "Previously, Beclin-1 has been shown to promote radiation-induced G2-M arrest in cancer cells." (PMID 40305155, 2025). "Additionally, in cancer cells, BECN1 promotes ferroptosis by directly interacting with xCT, thereby inhibiting system Xc− activity." (PMID 39940841, 2025). "Therefore, increasing research indicates the significance of pharmacological compounds in modulating Beclin-1 in human cancer and overseeing autophagy." (PMID 39650649, 2024). "Beclin-1 and ATGs regulate autophagy and cancer progression." (PMID 39650649, 2024).
cancer (continued). "Western blotting results determined that the extract significantly suppressed the growth of U2OS, MCF-7, and DU-145 cancer cells by down expression of Ang-1 (angiogenic protein) and Beclin-1 (autophagy protein) and overexpression of Bax (a proapoptotic protein)." (PMID 38560691, 2024). "Examining Beclin-1’s role reveals cancer cells’ reliance on autophagy for survival." (PMID 39650649, 2024). "PIKFYVE and PIP5K1A are enzymes targeted as therapies for cancer, as their inhibition has been shown to induce autophagy, further suggesting our compounds as inducers of autophagy, as both compounds led to an increase in beclin-1 levels." (PMID 39009412, 2024). "ECD domain important for Beclin-1 to regulate autophagy, prevent cancer." (PMID 39650649, 2024). "Moreover, the Beclin-1 signaling pathway has been implicated in the interplay between autophagy and EMT in cancer." (PMID 38398197, 2024). "The AMPK/Beclin-1 signaling pathway identified in this study may address this gap, offering a distinct mechanism for malignant cancer cells with bone metastasis that differs from previous findings." (PMID 39705435, 2024). "Disrupting the relationship between HMGB1 and Beclin-1/Bcl-2 may be an effective way to regulate autophagy, thus inhibiting the survival of cancer cells." (PMID 37897664, 2024). "Conversely, other studies have suggested that the upregulation of Beclin-1 may promote the mesenchymal phenotype in cancer cells." (PMID 38398197, 2024). "Targeting Beclin-1 for treatments may offer new approaches in cancer therapy, making it a potential biomarker and therapeutic target." (PMID 39650649, 2024). "Hence, it is recommended that upcoming research assess the relationship between the Beclin-1/autophagy axis and immunogenic cell death in treating human cancers." (PMID 39650649, 2024). "Together, Beclin 1 holds promise as a potential indicator for assessing the onset, invasion, metastasis, and prognosis of cancer, and may serve as a target for gene therapy in cancer." (PMID 39664581, 2024). "Even though the vast majority of our hits are known essential genes in human cancer cell lines or human iPSC-derived neurons, this method reveals some unique hits that have not been previously reported, including Jtb, Snx17, Psph, Bag1, and Becn1." (PMID 37398301, 2024). "Additionally, there have been reports stating that Beclin-1 controls autophagy, which can potentially affect apoptosis and ferroptosis in human cancer." (PMID 39650649, 2024). "In addition, Beclin-1 regulates autophagy in human cancers by interacting with ATGs, mTOR, and AMPK." (PMID 39650649, 2024). "Several studies have suggested that Beclin-1 may also play a role in the regulation of EMT in cancer." (PMID 38398197, 2024). "While increasing autophagy with Beclin-1 can help in some cases, it might promote cancer growth by supporting cell survival." (PMID 39650649, 2024). "Moreover, knockout experiments of autophagy-related proteins like ATG7, ATG5, and Beclin-1 enhanced the invasiveness of cancer cells in glioblastoma." (PMID 37893079, 2023). "In ICD-suffering cancer cells, upon knocking down Beclin-1, ATG5 or ATG7 could reduce the ATP release and consequently inhibit anticancer immunity in vivo." (PMID 36814780, 2023). "The expression level of ACC or BECN1 in AMPK-activated cancer cells may be critical in determining cell fate." (PMID 37842240, 2023). "Moreover, certain studies reflect the decrease in the level of Beclin-1 upon inflammation in cancers like hepatocellular carcinoma and cervical squamous cell carcinoma." (PMID 37893079, 2023). "NEDD4-1 can positively regulate the phagophore nucleation via targeting Beclin-1 in cancer cells." (PMID 36918822, 2023). "However, in all other cell lines, no changes in the expression levels of Beclin-1 by BSHE were observed according to studies dealing with Beclin-1-independent mechanisms of autophagy in cancer cells." (PMID 36891266, 2023).
cancer (continued). "Thus, the role of Beclin 1 expression on cell viability varies according to cancer cells with different histological origins." (PMID 37004094, 2023). "Moreover, cancer cell lines showed autophagy markers including Beclin-1 accumulation and LC3-II formation." (PMID 37834037, 2023). "Additionally, BECN1 knockdown largely improved the therapeutic effects of chemistry medicines in cancer treatment." (PMID 35012553, 2022). "Additionally, cancer cells knocked down for ATG5 or beclin-1 exhibited an enhanced radiosensitivity as a consequence of the inhibition of autophagy." (PMID 35054896, 2022). "Considering the pivotal role of BECN1 in the regulation of autophagy and its importance in cancer, more work is currently needed to understand the BECN1 splicing isoforms present in different cancers and how each isoform may affect autophagy." (PMID 36008963, 2022). "Considering the impact that short isoforms could have on cancer, we will also consider the investigation of pharmacological approaches to prevent the formation or neutralize the function of a specific short BECN1 isoform." (PMID 36008963, 2022). "Not only the initiation phase of autophagy could be regulated by miRNAs, but also the nucleation stage, in particular Beclin-1, which is one of the key players of autophagy in cancer." (PMID 35309939, 2022). "Considering this, researchers applied Se NPs in cancer cells and found that the autophagy induced by Se NPs participates in antitumor activities through elevating Beclin-1-related signaling pathways and downregulating p62, the protein which is inversely related to autophagy." (PMID 35958612, 2022). "In addition, Beclin-1 has an independent mechanism of autophagy and an independent role in autophagy in cancer." (PMID 35710416, 2022). "Gene deletion and reduced expression of Beclin-1 have been found in various cancer cells." (PMID 36104717, 2022). "Considering its role in balancing apoptosis with autophagy, BECN1 may play a dual role in cancer too by either stimulating apoptosis or autophagy." (PMID 36008963, 2022). "BECN1 has been confirmed to modulate apoptosis and autophagy in cancer cells." (PMID 35012553, 2022). "More investigation is needed to understand whether the short BECN1 isoforms maintain their functional role in other cellular processes or have any impact on cancer; (iv) BECN1-independent autophagy can occur." (PMID 36008963, 2022). "Although beclin 1 expression was required for ROS-induced autophagy, it has also been reported that anticancer agents can induce ROS-mediated beclin 1-independent autophagy in various cancer cell types." (PMID 35784738, 2022). "Together, these results indicate that Beclin1 levels modulate CSCs and autophagy through alternative pathways and targeting Beclin 1 may be effective in specific cancer types and stages." (PMID 33573362, 2021). "Furthermore, autophagy activated by Beclin-1 plays a crucial role in anticancer therapy: the resistance of cancer cells to some chemotherapy drugs enhances the autophagic process itself, increasing the survival of cancer cells." (PMID 34769649, 2021). "An example is beclin-1 (the protein indispensable in the membrane nucleation—phagophore formation stage, as well as autophagosome maturation) being attenuated in some cancers, such as breast, ovarian, prostate, cervical, lung, liver cancer, osteosarcoma, and glioblastoma." (PMID 34444893, 2021). "Dong and coworkers found cancers positively expressing Beclin-1 having a favorable prognosis." (PMID 34663249, 2021). "Reversely, Pug stimulated-cancer cells expressed the profile of markers associated with autophagy; increase in autophagic vacuoles, increase in microtubule-associated protein light chain 3 II (LC3-II) conversion, beclin-1 expression, and p62 degradation." (PMID 34444893, 2021).